INS (insulin)
Diseases named in the same sentence as INS in open-access papers (continued):
Sharing a sentence is not in itself a finding about the gene and the disease.
Glucose intolerance (continued). "Petrák and co-workers demonstrated impaired insulin secretion and glucose intolerance in patients with pheochromocytoma using meal test and the homeostasis model assessment of β-cell function (HOMA-β), which is surrogated marker of insulin secretion." (PMID 33324347, 2020). "Impairment of islet architecture, decreased islet insulin fluorescence intensity, and reduction of mean islet area in VAD diet-fed mice further suggested that VA altered the degree of glucose intolerance, which correlated with islet structure and β cell mass." (PMID 32064275, 2020). "Glucose intolerance develops promptly in rodents exposed to HFD, followed by a progressive increase of fasting insulin levels and metabolic derangements such as hepatic lipid accumulation." (PMID 32265637, 2020). "Further, the phosphorylation of AKT, a main metabolic sensor activated by insulin in the liver, was enhanced only in the DHT group, which was the only PCOS model showing glucose intolerance and AKT dephosphorylation." (PMID 32842637, 2020). "We also previously reported a protective effect of BAFF depletion against high-fat diet-induced glucose intolerance using BAFF−/− mice on a high-fat diet, which exhibited improved insulin sensitivity and potentiated adipose tissue function." (PMID 32698539, 2020). "In addition, METTL14 is essential for β-survival, differentiation and insulin secretion, the deficiency of METTL14 in β-cells increases cell death, changes cell differentiation and decreases β-cell mass and insulin secretion, leading to glucose intolerance and T2D." (PMID 32110378, 2020). "Methylglyoxal administration aggravated glucose intolerance (AUC0–120p < 0.05), and increased plasma glucose (p < 0.01) and insulin (p < 0.05)." (PMID 31388341, 2019). "Consistent with prior results, males with HFD donor BM had impaired insulin sensitivity as seen in insulin tolerance test (ITT) and glucose intolerance in males." (PMID 30944030, 2019). "In HFD-treated Nod1beta-cko mice, glucose intolerance was exacerbated compared to HFD-treated control mice and less insulin was secreted upon glucose challenge in vivo." (PMID 31201384, 2019). "Adjusted means of FPG, 2hPG, fasting insulin, HOMA-IR, T-Chol, Tg, and HDL-C levels varied significantly between the different stages of glucose intolerance." (PMID 30200612, 2018). "While NMN treatment ameliorated glucose intolerance in obese HFD-fed mice, Sirt2 knockdown partially negated the blood glucose-lowering effects of NMN in a glucose tolerance test when endogenous insulin secretion was inhibited by somatostatin administration." (PMID 29296001, 2018). "As such, fat derived adiponectin (insulin sensing promotor) and GLUT4 (insulin dependent glucose transporter) were significantly down-regulated in the HFD-C mice, resulting in glucose intolerance." (PMID 29409496, 2018). "Increased insulin secretion is characteristic of early T2DM, and in itself can contribute to the development of insulin resistance and glucose intolerance." (PMID 30233498, 2018). "Accordingly, these mice showed accelerated glucose intolerance already at 2 months of HFD (shown by oGTT), although plasma insulin levels apparently were unaltered." (PMID 30016962, 2018). "Along with impaired glucose intolerance, HFHF feeding induced insulinemia as evidenced by increased insulin AUC (60%, P = 0.023) after a glucose load and substitution of n-6 PUFA with n-3 PUFA corrected the HFHF induced insulinemia." (PMID 30026586, 2018). "In contrast to the glucose intolerance and mortality observed following acute administration of ritonavir to adult TG9 mice with dilated cardiomyopathy, improved glucose homeostasis, insulin sensitivity and survival was observed with chronic drug exposure." (PMID 29691457, 2018). "For example, mice with liver-specific KO of Pik3r1 demonstrate improved glucose tolerance and insulin-stimulated glucose uptake in skeletal muscle and are protected against HFD-induced glucose intolerance." (PMID 29997524, 2018).
Glucose intolerance (continued). "In our study, we observed that RES administration significantly reduced the AUC, improved HOMA-IR and increased insulin sensitivity in HFD-induced obese mice, which suggests that RES improved glucose intolerance and glucose homeostasis." (PMID 29967759, 2018). "Despite normal fasting glucose levels male ERV1tg developed some glucose intolerance upon intraperitoneal glucose administration compared to chow normal control diet (NCD) and delayed response to insulin." (PMID 28993702, 2017). "The glucose and insulin response to an OGTT was determined at baseline and again at the end of a glucose intolerance inducing diet." (PMID 28332596, 2017). "In another study, mice fed a KD during 12 weeks remained euglycemic, but had reduced mean serum insulin levels and HOMA-IR indices, and exhibited glucose intolerance as assessed by intra-peritoneal glucose tolerance tests." (PMID 28534852, 2017). "Comparison of the beta-cell function and insulin sensitivity between women with a normal OGTT and women with glucose intolerance postpartum." (PMID 27285104, 2016). "Adipocyte‐specific FADD deletion activated insulin signaling pathways in skeletal muscle, liver, and WAT, thereby contributing to the improvement of HFD‐induced whole‐body glucose intolerance." (PMID 27357657, 2016). "Consistent with the glucose intolerance profile of CUS-treated animals, insulin levels were significantly higher in CUS vs. control animals (p < 0.05)." (PMID 27538526, 2016). "Similarly, the emergence of glucose intolerance with age in βVps13cKO mice, which is reminiscent of changes seen after the inactivation of the T2D GWAS gene Tcf7l2 in mice, seems to reflect, at least in part, increasing insulin resistance as well as impaired insulin output from the pancreas." (PMID 27329800, 2016). "In order to explain the occurrence of glucose intolerance in pHF Wistar rats, plasma levels of adiponectin and FGF21, two modulators of insulin sensitivity, were determined." (PMID 27618559, 2016). "Both HFHS and OB/OB mice had higher daily caloric intake, associated with a significant increase in plasma fasting glucose, insulin, triglyceride, and cholesterol levels in comparison to C57 mice, and OGTT revealed the onset of glucose intolerance." (PMID 25750996, 2015). "Recently, it was reported that the whole-body glucose intolerance and IR observed in obese AIM wild-type mice were less severe in obese AIM knockout mice, as shown by intraperitoneal glucose and insulin tolerance tests." (PMID 24524410, 2014). "Moreover, there is an association of low serum phosphate levels with glucose intolerance, insulin sensitivity and insulin secretion in non-diabetic healthy-subjects and a phosphate deplete diet impairs rat insulin secretion (markedly reduced) by pancreatic islets ex vivo." (PMID 24839967, 2014). "Glucose intolerance was normalized with RU486 treatment, whereas acute insulin response was improved with RU486 and C113176 treatment." (PMID 24642683, 2014). "Since serum insulin, HOMA-IR and BMI were significantly attributable to a synergistic effect of glucose intolerance and FL, it is necessary to compare the interaction of these confounding factors together on serum TG." (PMID 23688034, 2013). "GTT experiments indicated that overexpression of Tff3 improved glucose intolerance, while ITT and PTT experiments suggested that Tff3 activation modestly enhanced insulin sensitivity and decreased glucose production in vivo in ob/ob mice, respectively." (PMID 24086476, 2013). "EPO treatment significantly reduced the body weights and the levels of fasting blood glucose and serum insulin and improved the HFD-induced glucose intolerance in mice." (PMID 23326455, 2013).
Glucose intolerance (continued). "In both cases, THCV appeared to affect fasting insulin and insulin levels after OGTT more profoundly than fasting glucose or glucose intolerance." (PMID 23712280, 2013). "Post-load blood glucose levels were increased in HFD-fed rats compared to CD-fed rats, whereas post-load plasma insulin levels remained unchanged after HFD and CD feeding, indicating mild glucose intolerance." (PMID 22716959, 2012). "To extend our knowledge regarding glucose intolerance in the PINX-P1 rats, we next performed insulin secretion experiments using islets isolated from the male offspring at ZT10." (PMID 22719949, 2012). "The paradoxical glucose intolerance despite low adiposity and low insulinemia in the renin transgenic male mice vs. control littermates led us to further investigate whether these differences were due to altered insulin sensitivity and/or glucose production or utilization in this model." (PMID 23308073, 2012). "In accordance with these findings, XYS/RTSES improved the regulation of blood glucose and increased the insulin sensitivity in the reserpine-induced glucose intolerance in mice, indicating that the antidepressant effect of XYS/RTSES may be partially caused by the improvement in glucose intolerance." (PMID 23134744, 2012). "It combines pronounced glucose intolerance and a moderately elevated FBG with almost normal insulin sensitivity when measured by FSI, 15SI, or HOMA-IR." (PMID 21592922, 2011). "While most PCOS women demonstrate preserved or even exaggerated insulin secretory responsiveness, many PCOS women, particularly those with a family history of T2DM, manifest secretory impairment and glucose intolerance." (PMID 21899727, 2011). "Administration of RSV for 5 weeks reduced the development of glucose intolerance, and increased portal vein concentrations of both Glucagon-like peptid-1 (GLP-1) and insulin, and intestinal content of active GLP-1." (PMID 21673955, 2011). "Taken together, these results suggest that the glucose intolerance induced by the COVID‐19 vaccine is mediated by impaired insulin sensitivity rather than impaired insulin secretion in mice." (PMID 41190280, 2025). "Therefore, as a predictor of T2DM before the onset of glucose intolerance, the FLI appears to be superior to the HOMA-IR and other insulin markers." (PMID 40570015, 2025). "Lactate and creatinine on hospital day 2 and 3, cardiovascular instability, high-dose vasopressor, low cardiac output, poor lactate clearance, glucose intolerance requiring insulin, and large aspiration were not significantly different between the groups." (PMID 40394230, 2025). "CIH did not modify body weight, glucose tolerance and insulin sensitivity at 1, 3 and 12 months of age, except for a transient increase in glucose intolerance observed in 3-month-old females, which was attenuated by 12 months." (PMID 41236084, 2025). "Under HFD feeding, glucose intolerance of BaβKO mice worsened, again without changes in insulin sensitivity." (PMID 41052246, 2025). "GG supplementation did not improve glucose homeostasis (i.e., glucose intolerance, insulin sensitivity, pancreatic β-cell dysfunction) and bone microstructure." (PMID 41465559, 2025). "Moreover, paternal CR or Met treatment normalized the glucose intolerance in AE-F2 males, as evidenced by significantly decreased blood glucose levels during IPGTT, while insulin sensitivity remained comparable." (PMID 39934105, 2025). "In this study, HFD feeding resulted in a significant increase in body weight and glucose intolerance in SAMP8 mice, as shown by the higher area under the curve (AUC) in GTT results, indicating poor glucose clearance and potential deterioration of insulin sensitivity." (PMID 39984825, 2025). "In addition, ablation of the proteasome activator PA28 leads to endoplasmic reticulum stress in the liver, which exacerbates glucose intolerance following liver IR and high-fat diet (HFD) exposure, ultimately disrupting insulin signal transduction." (PMID 41044789, 2025).
Glucose intolerance (continued). "In addition, we assessed the presence of glucose intolerance and the HOMA-IR using blood glucose and plasma insulin levels before feeding." (PMID 40074175, 2025). "Male SstKO-MSD mice, when compared to the SstKO mice born to the heterozygous mothers, showed worsened glucose intolerance without dietary challenge, albeit these mice had improved insulin sensitivity evidenced in the insulin tolerance test." (PMID 40066865, 2025). "Global Redd2-KO ameliorated glucose intolerance by increasing β-cell mass and insulin concentrations without affecting insulin sensitivity in HFD-fed mice." (PMID 40409543, 2025). "In the animals fed with a high-fat diet without LHBGRA43, glucose and insulin levels, as well as the indicators of systemic glucose intolerance, the HOMA index and the AUC-IPGTT value, were elevated compared to the control animals (p < 0.01)." (PMID 41262214, 2025). "Glucose intolerance was accompanied by significantly reduced plasma insulin levels during the intraperitoneal glucose tolerance test, confirming the lack of insulin secretion in Ins2‐Tipe1BKO‐db/db mice." (PMID 38417114, 2024). "In addition to whole body and adipose tissues weight gains, glucose intolerance was observed after 5 and 9 weeks of HFHSD and resistance to insulin after 13 weeks, illustrating the progressive alteration of the glucose metabolism by the HFHSD." (PMID 38542714, 2024). "Therefore, calcium ions are not able to influx from the extracellular space and there will be impaired secretion of insulin resulting in the defective metabolism of glucose and, for example, NDM-impaired fasting sugar, glucose intolerance, and KCNJ11-MODY." (PMID 38675722, 2024). "Glucose intolerance and normal insulin sensitivity in male mice under CJL suggest that not only the insulin response to glucose but also the glucose disposal process is inhibited under CJL conditions via insulin-independent glucose disposal mechanisms." (PMID 39639385, 2024). "Restoring expression of MC4Rs specifically in the lateral hypothalamic nucleus improves glucose intolerance in obese MC4R-null mice through bilateral interscapular brown adipose tissue denervation without affecting body weight or circulating insulin levels." (PMID 38448811, 2024). "Qing110 treatment significantly alleviated glucose intolerance in Atm−/− mice, as indicated by oral glucose tolerance tests, and enhanced insulin sensitivity compared to the PBS-treated Atm−/− mice, as shown by insulin tolerance tests." (PMID 38364095, 2024). "For example, blocking the ligand effect of ghrelin through the antagonist and ghrelin knockout prevented HFD-induced glucose intolerance; in the study, antagonism of ghrelin enhanced insulin release without altering insulin sensitivity." (PMID 38794702, 2024). "Conversely, others who have studied intra-islet GCGR signalling in germline or conditional β-cell knock out of the GCGR using a mouse insulin promoter (MIP)Cre-driven mechanism have not reported glucose intolerance." (PMID 38677509, 2024). "Other studies have shown that circadian rhythm disruption can specifically induce glucose intolerance mainly by lowering insulin sensitivity, not by affecting pancreatic beta-cell function." (PMID 38393018, 2024). "In other words, ADP is unlikely to explain the link between CF liver disease and glucose intolerance as well as the relationship between reduced insulin sensitivity and CFRD." (PMID 39530118, 2024). "Glucose-induced insulin release is reduced in islet cells lacking the clock gene Bmal1, and these mice exhibit glucose intolerance." (PMID 38393018, 2024). "The delayed glucose intolerance in females is not surprising, as female mice are known to display improved glucose tolerance and increased insulin sensitivity, in part due to the action of sex hormone regulation of metabolism." (PMID 38840215, 2024).
Glucose intolerance (continued). "Moreover, our findings align with an earlier study using global-Sucnr1-knockout mice, which exhibited progressive glucose intolerance under HFD and an impaired insulin response, occurring as part of a complex phenotype." (PMID 38713514, 2024). "Prior research has indicated that upregulation of GLUT4 in adipose tissue improves insulin sensitivity; however, this is, by itself, not enough to protect against the damaging effects of diet-induced glucose intolerance." (PMID 39596898, 2024). "Furthermore, HFD led to increased FBG (p < .01) and glucose intolerance (assessed through GTT) (p < .01) and decreased insulin sensitivity (assessed through ITT) (p < .01)." (PMID 38599845, 2024). "The present study aimed to clarify the relationships between novel and traditional anthropometric indices and insulin sensitivity (SI) in young and middle-aged Japanese persons with normal glucose tolerance (NGT), and middle-aged Japanese persons with NGT and glucose intolerance." (PMID 38190317, 2024). "In this study, we observed that although GDM patients still show glucose intolerance at delivery, plasma insulin and HOMA-IR have returned to normal levels." (PMID 38791090, 2024). "On the other hand, a previous study did not detect any differences in insulin clearance in those with glucose intolerance in a young CF population (10–25 years) excluding those receiving insulin treatment." (PMID 39093413, 2024). "In CF, ADP was negatively correlated with hepatic insulin resistance as well as low fat, muscle, and bone mass, but not with glucose intolerance." (PMID 39530118, 2024). "Defects in insulin and IGF1 signaling pathways were also found to be responsible for decompensation of β‐cell proliferation and mass, which contributes to disturbance of insulin secretion and glucose intolerance in T2DM." (PMID 36891946, 2023). "After noticing eTRF males developed glucose intolerance after HFHS diet exposure in both cohorts, we sought to explore cohort 2 more closely for insulin secretion defects, via an in vivo glucose-stimulated insulin secretion (GSIS) assay." (PMID 37808966, 2023). "HOMA-IR has been used as an indicator of insulin sensitivity in cats, and the overweight and obese cats used in this study had HOMA-IR calculations consistent with reported values for obese and overweight glucose intolerance." (PMID 36756310, 2023). "This resulted in a similar but more severe phenotype characterized by heavily impaired growth (Fig EV3B and C), greater glucose intolerance, and impaired insulin secretion (Fig EV3D and E), as well as complete absence of INS1/INS2 expression (Fig EV3F)." (PMID 37712288, 2023). "Because pemafibrate is reported to improve glucose intolerance in mice treated with a high fat diet and a novel selective PPARα modulator, it may affect KATP channels or insulin secretion." (PMID 37697384, 2023). "Treatment of young‐adult rats with clopidogrel also resulted in glucose intolerance, and lower glucose‐stimulated insulin secretion, but did not affect insulin sensitivity (Fig EV5D–F)." (PMID 37490001, 2023). "Moreover, the management of glucose intolerance in PPGL patients is often challenging: glycemic disturbances are frequently severe and difficult to treat, requiring, in some cases, insulin therapy." (PMID 36982228, 2023). "In summary, 2 obese mouse models under excessive or physiological CORT levels revealed that there is muscle GR–originated and insulin-mediated metabolic communication involving WAT, liver, and skeletal muscle, which is crucial to the induction of body composition changes and glucose intolerance." (PMID 36917179, 2023). "The Ctnna1ΔEndo/ΔEndo mice exhibited glucose intolerance, but no detectable difference in insulin secretion compared to control littermates." (PMID 37610090, 2023).